IL6 (interleukin 6)
Diseases named in the same sentence as IL6 in open-access papers (continued):
Sharing a sentence is not in itself a finding about the gene and the disease.
Hypertension (continued). "Consistent with our findings, the incidence of T2DM significantly increases among individuals with a family history of both hypertension and hypercholesterolemia, as well as with increased levels of inflammatory biomarkers, i.e., C-reactive protein and interleukin-6, as reported by others." (PMID 38668310, 2024). "For example, IL-6 impacts the body’s reactions to angiotensin II infusion, even in patients with normal blood pressure, but IL-17 plays a vital role in the development of hypertension." (PMID 38672199, 2024). "Thus, IL-6 has been shown to contribute to hypertension progression, and its levels are depressed by blood pressure-lowering therapies." (PMID 38256155, 2024). "Therefore, the increases in pro-inflammatory and inflammatory cytokines such as IL-1β, IL-6, and IL-8 in monocytes lead to systemic inflammation and worsen metabolic syndrome, including hypertension in SAS patients." (PMID 38276286, 2024). "Meanwhile, in patients with chronic CSC, elevated plasma levels of IL-8, IL-6, and TNF-α were found to be associated with hypertension, shedding light on the potential role of these cytokines in the pathophysiology of chronic CSC and its associated comorbidities." (PMID 38835666, 2024). "Additionally, the level of IL-6, a key inflammation biomarker, was significantly higher in hypertension APs than that in non-hypertension APs." (PMID 38666774, 2024). "It has been found that NF-κB can mediate a variety of inflammatory responses, and activation of the NF-κB signaling pathway induces an increase in the expression of TNF-α and IL-6, which leads to hypertension and contributes to the development of cardiac remodeling." (PMID 38680497, 2024). "The cytokine may enhance the blood pressure via synergism with the Renin-Angiotensin Aldosterone System (RAAS) since IL-6 deletion blunted the angiotensin II (AngII)-induced hypertension in mice." (PMID 39723211, 2024). "Although details linking IL-6 to the blood pressure remain to be clarified, the cytokine has been increasingly recognized as a key player connecting chronic inflammation to hypertension." (PMID 39723211, 2024). "It has been reported that IL-6 inhibition attenuates hypertension and blunts the infiltration or proliferation of macrophages and mononuclear cells into the kidneys, thereby reducing hypertension-related renal damage in Dahl salt-sensitive rats." (PMID 38632649, 2024). "IL-6 is related to angiotensin II (Ang-II)-mediated hypertension." (PMID 37273529, 2023). "The inhibition of individual IL-6 ameliorates the development of experimental hypertension." (PMID 37920615, 2023). "This study comprehensively evaluated the changes of inflammation caused by high-salt diet in rats from the aspects of inflammatory cytokines (TNF-α, IL-8, IL-1β, and IL-6) and hormones related to hypertension (NE, LEP, and Ang II), and Vascular and renal lesions were also examined." (PMID 36925479, 2023). "Prolonged hypertension leads to the systemic release of cytokines, including interleukin 17, interferon gamma, tumor necrosis factor-α, and interleukin 6, which contribute to renal fibrosis, alter sodium membrane transportation, and increase oxidative stress and arterial stiffness." (PMID 37842465, 2023). "Similarly, the risk of pregnancy-induced hypertension was higher in individuals whose blood serum had elevated levels of oxidative stress factors such as TNF-α, interleukin-6, and interferon-γ." (PMID 37685488, 2023). "A study comparing healthy and “almost healthy” persons defined by the lack of exercise or by the use of medications for chronic conditions such as hypertension or osteoarthritis demonstrated lower levels of interleukin 2 and higher levels of interleukin 6 in the latter." (PMID 37780417, 2023). "However, dietary approaches to arrest hypertension and a plant-based dietary model have been shown to be beneficial in reducing IL-6 and CRP levels." (PMID 38077946, 2023).
Hypertension (continued). "Furthermore, T-cells are shown to be deregulated in hypertension and CVDs, resulting in an increased production of the pro-inflammatory cytokines IL-6, IL-7, IFN-γ, and TNF-α." (PMID 37238657, 2023). "Here, the functions of IL-6 in hypertension and anxiety were unclear." (PMID 37273529, 2023). "IL-6 may trigger obesity by inducing hepatic gluconeogenesis and inhibiting lipid metabolism, thereby facilitating hypertension." (PMID 37273529, 2023). "For instance, miR-214 exacerbates kidney damage and inflammation induced by hyperlipidemic pancreatitis, it mediates perivascular fibrosis in hypertension and it is involved, together with IL-6/STAT3, in ulcerative colitis pathogenesis where its targeting reduces the severity of the disease." (PMID 36639824, 2023). "In addition, some studies have found that people with hypertension have elevated levels of circulating inflammatory cytokines, including IL-6, IL-1β, and TNF-α." (PMID 36937901, 2023). "Furthermore, monocyte-derived derived DCs from hypertensive mice produce increased amounts of ROS, IL-1β, TNF-α, IL-6, and IL-23 to promote hypertension and end-organ damage." (PMID 37266014, 2023). "In hypertension studies, baicalin reduced hypertension-induced inflammation (significant reduction in IL-1β and IL-6) by increasing the expression of tight-junction proteins that could maintain intestinal integrity." (PMID 37298268, 2023). "Increased IL-6, IL-17, and ROS accelerate the development of hypertension and anxiety." (PMID 37273529, 2023). "Additionally, this study described some common underlying mechanisms of hypertension and anxiety, including IL-6, IL-7, ROS, and gut dysbiosis, which are expected to become therapeutic targets for patients with comorbid hypertension and anxiety." (PMID 37273529, 2023). "IL-6 levels were increased in 63% of patients with significant differences in the distribution across the following groups; age, disease severity, hospitalisation status, pulmonary infiltrates, oxygen therapy, and hypertension status." (PMID 35873360, 2022). "Interleukin-6 (IL-6), elevated in hypertension, is known to suppress LOX expression." (PMID 35885053, 2022). "Moreover, IL-6 is probably involved in hypertension considering its role in vascular inflammation, angiosclerosis and endothelial dysfunction." (PMID 36195874, 2022). "Concerning this, different studies have found that practices such as cooking with biomass are associated with increased IL-6, IL-8, and TNF-α, neutrophil infiltration, increased oxidative stress, hypertension, and tachycardia, increasing the risk of cardiovascular diseases." (PMID 35534522, 2022). "Associations between hypertension with TNF-α, IL-6, and CRP have been reported, suggesting that inflammation may link cataract and hypertension." (PMID 35565652, 2022). "The aim of this study is to assess proinflammatory status serum indicators (C-reactive protein (CRP), tumor necrosis factor alpha (TNF-α), interleukin-6 (IL-6)) in middle-aged males (M) and females (F) with essential hypertension (HTN) depending on left ventricular (LV) diastolic dysfunction (LVDD)." (PMID 35997392, 2022). "Furthermore, increased maternal serum levels of IL-6 and TNF-α have been associated with hypertensive disorders during pregnancy." (PMID 36012236, 2022). "On linear regression, 2-Methylbutyrate was the most predictive SCFA for systemic IL-6 levels, while Butyrate was the most predictive of intracranial IL-6 levels, and the strength of both models improved when hypertension was included as a predictor in the models." (PMID 35126360, 2021). "Preclinical evidence has indicated that interleukin 6 (IL-6) may play a role in mediating hypertension and reducing renal hemodynamics observed in uterine perfusion reductions in pregnant rats." (PMID 34906255, 2021).
Hypertension (continued). "HHcy synergistically aggravated the arterial damage factor of hypertension through NF-κB p65/Rela/IL-6 signaling pathway, which could be the target of folate against immune/inflammation." (PMID 34603014, 2021). "In hypertension, IL-6 can increase and act as a pro-inflammatory factor." (PMID 34777003, 2021). "Plasma IL-6 levels strongly correlate with hypertension in humans." (PMID 34441038, 2021). "IL6 is also involved in Ang-II induced micro-vascular dysfunction and hypertension." (PMID 33807627, 2021). "In pregnant rats, Orshal and Khalil found that IL-6 enhanced vascular resistance and hypertension." (PMID 34806090, 2021). "The macroalbuminuria and renal failure groups had higher prevalences of a history of hypertension, and higher IL-6 and IL-8 concentrations, but lower serum Zn, 24 h urine Zn loss, 24 h urine Mg loss, and eGFR than the normal and microalbuminuria groups (P < 0.05)." (PMID 33859989, 2021). "Likewise, studies report a correlation between cytokines such as IL-6, TNFα, and C-reactive protein and blood pressure in patients with essential hypertension." (PMID 33953971, 2021). "Recently, elevated plasma inflammatory markers, including hs-CRP and IL-6, have been reported to be nonsignificantly related to a higher risk of hypertension." (PMID 32292598, 2020). "IL-17 and IL-6 secreted by the Th17 cells promoted a renal and vascular dysfunction and damage, which resulted in the increased water-sodium retention and systemic vascular resistance and further exacerbated the development of hypertension." (PMID 32724324, 2020). "Besides IL-6 increase in plasma observed in Ang-II hypertension is due to the rise in aldosterone levels, at least in the early stages of hypertension." (PMID 32848763, 2020). "There is substantial evidence that IL-6 has an important role in the hypertension pathogenesis." (PMID 32848763, 2020). "At Cox regression analysis, significant predictors of in-hospital mortality were: hypernatremia (HR 9.12), lymphocyte count < 1000 cells/μL (HR 7.45), cardiovascular diseases other than hypertension (HR 6.41), and higher levels of serum interleukin-6 (IL-6, pg/mL) (HR 1.005)." (PMID 33257703, 2020). "Hypertension causes increased release of both ICAM-1 and IL-6; that in turn stimulate CRP release." (PMID 33204538, 2020). "However, sex, hypertension, IL-6, T lymphocyte count, B lymphocyte count, glucocorticoid treatment and artificial liver support were not recognized as independent factors." (PMID 33302889, 2020). "Compared to pneumonia-free patients, pneumonia patients were 16.5 years older and had higher frequencies of having hypertension, fever, and cough and higher circulating levels of neutrophil proportion, interleukin-6, low count (< 190/μl) of CD8+ T cells, and neutrophil/lymphocyte ratio." (PMID 33239109, 2020). "Importantly, hypernatremia, lymphopenia, CVD other than hypertension, and higher IL-6 serum level appeared to be independent predictors of in-hospital mortality." (PMID 33257703, 2020). "Adiponectin decreases the production of angiotensin II and thereby promotes high blood pressure while resistin is associated with increases in TNF-α receptor-2 and IL-6, leading to increased level of endothelin which constricts blood vessels and raises blood pressure." (PMID 33014422, 2020). "Indeed, we found that ginseng intake decreased the levels of cytokines, including IL-1β, IL-6, and TNF-α, and factors associated with high blood pressure, including ACE activity and angiotensin II." (PMID 32727012, 2020). "Furthermore, a number of studies indicated that IL-6 has an important role in the pathophysiology of several diseases, including hypertension, atherosclerosis, vascular occlusive disease, and vascular remodeling." (PMID 31703282, 2019). "In addition, it has been shown that the plasma levels of IL-6 are high in patients with hypertension and unstable angina." (PMID 31703282, 2019).
Hypertension (continued). "The exact process relating to decreased methylation of the pro-inflammatory cytokine, IL-6 to pre-hypertension is unknown." (PMID 31908586, 2019). "IL-6 methylation could be an important indicator for predicting future hypertension in young adults." (PMID 31908586, 2019). "Furthermore, APN, CTRP1, and IL-6 were three factors that influenced the STOD of EH patients, among which CTRP1 and IL6 were positively related with the complication of hypertension and STOD." (PMID 31772610, 2019). "In the present study, 12-week-old SHR exhibited higher expression of inflammatory factors including TNF-α, IL-1β, IL-6, and iNOS at both mRNA and protein levels, which could be aggravated with the progress of hypertension and attenuated by captopril treatment." (PMID 30183974, 2018). "Adjusting for IL-6 and C-reactive protein as well as hypertension, physical inactivity, and low FEV, led to further marked attenuation of the socioeconomic gradient in frailty, in line with the role of serum C-reactive protein concentration in predicting ADL disability." (PMID 29908857, 2018). "Nevertheless, some studies have showed that IL-6 attenuation could attenuate angiotensin II–induced hypertension and kidney injury." (PMID 29461477, 2018). "Notably, both animal and human studies reported that elevated IL-6 expression levels contribute to the pathogenesis of chronic kidney disease in hypertension." (PMID 29461477, 2018). "IL-6 is fundamental for the development of stress-induced hypertension." (PMID 30151015, 2018). "Interventions to enhance bioavailable NO, reduce IL-6 or hydrogen peroxide production or to inhibit STAT3 may have anti-inflammatory roles in hypertension and related conditions." (PMID 29800237, 2018). "The cytokine Interleukin-6 (IL-6) is a fundamental mediator of the acute-phase response to endothelial injury and regulates the production of C Reactive Protein (CRP) in hepatocytes; therefore, both IL-6 and CRP genetic variants have been evaluated in relation to hypertension." (PMID 29495593, 2018). "In contrast, IL-6 appears to contribute, in part, to the maintenance of the hypertensive phenotype as IL-6-deficiency is limits the rise in arterial pressure associated with some, but not all, forms of experimental hypertension." (PMID 29186034, 2017). "Nonetheless, IL-6 mediates many of the negative effects associated with hypertension and angiotensin II on vascular structure and function independent of blood pressure." (PMID 29186034, 2017). "IL-6 is increased in a number of cardiovascular diseases, including hypertension." (PMID 29186034, 2017). "Moreover, DCs secrete cytokines such as IL-1β, IL-6, IL-23 which promote polarization of T lymphocytes to Th17 cells, which plays particular role in hypertension development." (PMID 28838042, 2017). "Furthermore, we found that higher CMV IgG titer and CRP levels were an independent risk factor of hypertension progression and hypertensive TOD and that CMV IgG titers were positively correlated with CRP and IL-6 levels." (PMID 28837559, 2017). "IL-6 levels also had a significant positive relationship with higher grade of BP in all models (model 3, P = 0.022; others, P = 0.002) and higher grade of hypertension in model 1 (P = 0.024)." (PMID 28837559, 2017). "Specifically, we determined whether the requirement for IL-6 for AngII to induce ∼25 mmHg of hypertension is due to the fact that blood pressure is above normal." (PMID 26486161, 2015).
Hypertension (continued). "This study determined the role of interleukin-6 (IL-6) in the physiologic effect of AngII to maintain normal MAP during low-salt (LS) intake, and whether hypertension induced by plasma AngII concentrations measured during LS diet required IL-6." (PMID 26486161, 2015). "Among the commonly used medications, dihydropyridine derivatives (ATC: C08CA, 54 users), often used to treat hypertension, were correlated to increased IL-6 levels, whereas glucocorticoids (ATC: R03BA, 26 users) lowered both Basigin and hepatocyte growth factor (HGF) receptor levels." (PMID 25147954, 2014). "However, some significant differences were seen in TRPA1 KO mice during hypertension; notably, a trend for increased hypertrophy and a blunted increase in IL-6." (PMID 25505598, 2014). "In humans, many lines of evidence that established essential hypertension as a condition of chronic low-grade inflammatory status also revealed a strict and independent association between CRP, TNF-α, and IL-6 or adhesion of molecules and vascular changes in essential hypertensive patients." (PMID 25143940, 2014). "Expression of IL-6, a cytokine implicated in vascular disease and hypertension, was not altered in old wild-type, but was increased substantially in old IL-10 knockout mice." (PMID 24400151, 2013). "Recently, we have found that prenatal exposure to lipopolysaccharide (LPS), which is commonly used to mimic prenatal infection, could result in increased TNF-α and IL-6 levels in pregnant rats and induce hypertension in adult offspring." (PMID 24764457, 2013). "The protective effect of three IL-6 SNPs for LOAD was especially evident among participants with hypertension, which may be a result of medication for treating hypertension that can lower inflammatory responses." (PMID 22272811, 2012). "Animal studies showed that infusion of IL-6 induces hypertension in pregnant rats." (PMID 22269218, 2012). "IL-6 stimulates the central nervous system and sympathetic nervous system, which may result in hypertension." (PMID 18416854, 2008). "Polymorphisms in the IL-1β, IL-6, and TNF-α genes have been associated with an increased risk and severity of CVD, particularly influencing factors such as ulceration, age of disease onset, and comorbid conditions like arterial hypertension and ischemic heart disease." (PMID 39857734, 2025). "However, actually, comorbidities such as type 2 diabetes (T2DM) and hypertension may worsen psychosomatic syndromes through IL-6 and other inflammatory markers." (PMID 40708589, 2025). "The pro-inflammatory cytokines, such as TNF-α, IL-1β, and IL-6, which have been extensively studied for their implication in the pathogenesis of heart failure, were not elevated in the heart tissue, most probably due to a short period of exposure to hypertension." (PMID 40422564, 2025). "This is of particular interest, as recent studies suggest that a higher IL-6/TNF ratio is associated with impaired vasodilation, increased arterial stiffness, and elevated sympathetic tone—mechanisms that can contribute to persistent or recurrent hypertension after aortic arch intervention." (PMID 41010423, 2025). "The clinical implications of these biochemical changes in interleukins and their relationship with hypertension remain unclear, but it is important to note that recent scientific evidence has consistently highlighted the impact of IL-6 on arterial hypertension." (PMID 40002786, 2025). "Hypertension may also raise IL-6 and IL-17 levels, contributing to chronic inflammation." (PMID 38424126, 2024). "Assuming that inflammation may be the underlying mechanism in the relationship between MASLD and hypertension, we evaluated cytokines (TNF-α, IL-6, IL-10, IL-4, and IL-13) in the liver of patients with morbid obesity, MASLD, and SAH compared to patients without SAH." (PMID 39337863, 2024).